ZNF34 (zinc finger protein 34)
Description:
May be involved in transcriptional regulation.
Synonyms: KOX32
Tractability: PROTAC: ubiquitination databases record sites on it.
Gene: Protein-coding gene on chromosome 8 (144,772,224 to 144,788,684, reverse strand). Ensembl gene ENSG00000196378.
Subcellular location: Nucleus
Subcellular location (Human Protein Atlas): Nucleoplasm; Cytosol
Pathways (Reactome):
Gene expression (Transcription): Generic Transcription Pathway
Gene Ontology:
Molecular function: protein binding; DNA-binding transcription factor activity, RNA polymerase II-specific; RNA polymerase II cis-regulatory region sequence-specific DNA binding
Biological process: regulation of transcription by RNA polymerase II; regulation of DNA-templated transcription
Cellular component: cytosol; nucleoplasm; nucleus
Genetic constraint (gnomAD): Loss-of-function variants: 8 observed, 12.72 expected, observed/expected ratio (o/e) 0.63, 90% interval 0.37 to 1.13. The upper end of that interval is the gene's LOEUF score, 1.13, which puts it in group 4 of 6, group 1 being the genes least tolerant of losing a copy. Missense variants: 538 observed, 684.49 expected, observed/expected ratio (o/e) 0.79, 90% interval 0.73 to 0.84. Synonymous variants: 235 observed, 247.61 expected, observed/expected ratio (o/e) 0.95, 90% interval 0.85 to 1.06.
Homologues: Orthologues: chimpanzee ZNF34 (99% identical), macaque ZNF34 (95% identical), dog ZNF34 (86% identical), pig ZNF34 (84% identical), rabbit ZNF34 (73% identical), mouse Zfp534 (43% identical), mouse Zfp987 (43% identical), mouse Zfp988 (43% identical), mouse Zfp989 (42% identical), mouse Rex2 (42% identical), mouse Gm7072 (42% identical), mouse Zfp760 (42% identical), and 29 more. Paralogues in human: ZNF287 (46% identical), ZNF527 (42% identical), ZKSCAN7 (41% identical), ZNF416 (41% identical), ZNF17 (41% identical), ZNF852 (40% identical), ZNF214 (40% identical), ZNF530 (40% identical), ZNF572 (37% identical), ZNF587 (37% identical), ZNF285 (37% identical), ZNF417 (36% identical), and 38 more.
Diseases named in the same sentence as ZNF34 in open-access papers:
ZNF34 is named in the same sentence as 4 diseases in open-access papers, as found by Europe PMC text mining. Sharing a sentence is not in itself a finding about the gene and the disease.
ZNF34 shares sentences with these, for which no sentence is quoted: cognitive deficit (1 paper); diabetes (1); schizophrenia (1); type 2 diabetes (1).